SCP2 (sterol carrier protein 2)
Description:
[Isoform SCPx]: Plays a crucial role in the peroxisomal oxidation of branched-chain fatty acids. Catalyzes the last step of the peroxisomal beta-oxidation of branched chain fatty acids and the side chain of the bile acid intermediates di- and trihydroxycoprostanic acids (DHCA and THCA). Also active with medium and long straight chain 3-oxoacyl-CoAs. Stimulates the microsomal conversion of 7-dehydrocholesterol to cholesterol and transfers phosphatidylcholine and 7-dehydrocholesterol between membrances, in vitro (By similarity). Isoforms SCP2 and SCPx cooperate in peroxisomal oxidation of certain naturally occurring tetramethyl-branched fatty acyl-CoAs (By similarity). [Isoform SCP2]: Mediates the transfer of all common phospholipids, cholesterol and gangliosides from the endoplasmic reticulum to the plasma membrane. May play a role in regulating steroidogenesis. Stimulates the microsomal conversion of 7-dehydrocholesterol to cholesterol (By similarity). Also binds fatty acids and fatty acyl Coenzyme A (CoA) such as phytanoyl-CoA. Involved in the regulation phospholipid synthesis in endoplasmic reticulum enhancing the incorporation of exogenous fatty acid into glycerides. Seems to stimulate the rate-limiting step in phosphatidic acid formation mediated by GPAT3. Isoforms SCP2 and SCPx cooperate in peroxisomal oxidation of certain naturally occurring tetramethyl-branched fatty acyl-CoAs (By similarity).
Synonyms: SCP-2; NSL-TP; SCP-X; nsLTP; SCPx; NLTP; SCOX; SCP-CHI
Tractability: Small molecule: it belongs to a druggable protein family. PROTAC: ubiquitination databases record sites on it; its protein half-life has been measured; a small molecule that binds it is known.
Target class: Enzyme
Gene: Protein-coding gene on chromosome 1 (52,927,276 to 53,051,698, forward strand). Ensembl gene ENSG00000116171.
Subcellular location: Peroxisome (Isoform SCP2); Cytoplasm; Mitochondrion; Endoplasmic reticulum; Peroxisome (Isoform SCPx)
Subcellular location (Human Protein Atlas): Peroxisomes; Nucleoplasm
Pathways (Reactome):
Metabolism: Beta-oxidation of pristanoyl-CoA; Synthesis of bile acids and bile salts via 7alpha-hydroxycholesterol; alpha-linolenic acid (ALA) metabolism
Protein localization: Peroxisomal protein import; TYSND1 cleaves peroxisomal proteins
Gene Ontology:
Molecular function: cholesterol binding; fatty-acyl-CoA binding; long-chain fatty acyl-CoA binding; oleic acid binding; propionyl-CoA C2-trimethyltridecanoyltransferase activity; protein binding; signaling receptor binding; acetyl-CoA C-acyltransferase activity; acetyl-CoA C-myristoyltransferase activity; acyltransferase activity; acyltransferase activity, transferring groups other than amino-acyl groups; fatty acid binding; propanoyl-CoA C-acyltransferase activity
Biological process: lipid hydroperoxide transport; positive regulation of intracellular cholesterol transport; alpha-linolenic acid metabolic process; bile acid biosynthetic process; bile acid metabolic process; fatty acid beta-oxidation; fatty acid beta-oxidation using acyl-CoA oxidase; fatty acid biosynthetic process; fatty acid oxidation; regulation of lipid metabolic process; sterol transport
Cellular component: cytoplasm; membrane; mitochondrion; peroxisome; protein-containing complex; cytosol; endoplasmic reticulum; peroxisomal matrix
Genetic constraint (gnomAD): Loss-of-function variants: 23 observed, 34.51 expected, observed/expected ratio (o/e) 0.67, 90% interval 0.48 to 0.94. The upper end of that interval is the gene's LOEUF score, 0.94, which puts it in group 4 of 6, group 1 being the genes least tolerant of losing a copy. Missense variants: 344 observed, 387.27 expected, observed/expected ratio (o/e) 0.89, 90% interval 0.81 to 0.97. Synonymous variants: 133 observed, 132.01 expected, observed/expected ratio (o/e) 1.01, 90% interval 0.87 to 1.16.
Gene-disease validity (ClinGen):
ClinGen rates the evidence that SCP2 causes each of these diseases.
sterol carrier protein 2 deficiency (autosomal recessive): Definitive. A peroxisomal neurodegenerative disorder characterized by spasmodic torticollis, dystonic head tremor, intention tremor, nystagmus, hyposmia, and hypergonadotrophic hypogonadism with azoospermia.
Homologues: Orthologues: chimpanzee SCP2 (99% identical), macaque SCP2 (98% identical), mouse Scp2 (89% identical), rabbit SCP2 (89% identical), dog SCP2 (86% identical), tropical clawed frog scp2 (77% identical), Drosophila melanogaster ScpX (58% identical), zebrafish scp2b (19% identical). Paralogues in human: SCP2D1 (10% identical).
Diseases named in the same sentence as SCP2 in open-access papers:
SCP2 is named in the same sentence as 82 diseases in open-access papers, as found by Europe PMC text mining. Sharing a sentence is not in itself a finding about the gene and the disease. The quoted sentences say what the papers report.
breast carcinoma (10 papers, 2012 to 2023). "Inhibition of SCP2 was also found to increase cell viability in GPX4-/- fibroblasts or RSL3-treated breast cancer cells." (PMID 37422468, 2023). "Despite silico-derived data being obtained from a small number of patients, we were able to identify ALDH1A3, MED20, PABPC4, SLC26A11 and SCP2 as deregulated genes in diabetic breast cancer patients, which coincided with our microarray data." (PMID 37511575, 2023). "Although in this study we have not focused on SCP2, future work is planned to study the role of SCP2 in breast cancer in relation to hyperglycemia and hyperinsulinemia." (PMID 37511575, 2023). "As we know, inhibition of SCP2 increases cell viability in GPX4-/- fibroblasts or RSL3-treated breast cancer cells, but the mechanism driving this remains obscure." (PMID 37422468, 2023). "Active TGF-β signaling activity in SCP2 breast cancer cells, measured by pSmad2 levels, was increased after incubation with Hs27a supernatant." (PMID 26203666, 2015). "Together, these results suggest that SOST in breast cancer cells may promote the proliferation of SCP2 cells by activating the TGF-β/RAS signaling, and promotes bone metastasis by upregulating CXCR4 expression." (PMID 36581888, 2022). "We report experimental results using a modification of the transmembrane assay, demonstrating the hindrance of migration of breast cancer cells (SCP2) when an induced a.c. electric field is present in the appropriate direction (i.e. in the direction of migration)." (PMID 26055698, 2015). "To address the importance of p21 and cyclin D1 on breast cancer development in vivo, we injected either SCP2 control or double p21 and cyclin D1 knockdown cells into the mammary fat pads of female Balb/c nude mice to monitor primary tumor growth and local invasiveness." (PMID 23786849, 2013). "In mono-cultures of SCP2, ZOL increased breast cancer cell death after 48 hours compared to control from 4.3 ± 1.4 % to 11.8 ± 2.3 % (P < 0.05) for 100 μM and 18.4 ± 3.3 % (P < 0.001) for 500 μM ZOL." (PMID 26203666, 2015). "The breast cancer cell fraction of tumors containing only SCP2 or MCF-7 cells was not affected by ZOL." (PMID 26203666, 2015). "Interestingly, we found that while TGFβ did not induce association between p21 and p300/CBP, it strongly induced complex formation between p21 and p/CAF in both SCP2 and SUM159 breast cancer cells." (PMID 22995475, 2012).
Dystonia (8 papers, 2016 to 2023). An abnormally increased muscular tone that causes fixed abnormal postures. "One prenatal ultrasound revealed omphalocele and NT thickening, whereas WES revealed the SCP2 gene inherited from the mother and associated with leukodystrophy with dystonia and motor neuropathy." (PMID 37726736, 2023). "SCP2 is responsible for mediating the transfer of common phospholipids, cholesterol, and gangliosides, and is implicated in Leukoencephalopathy with Dystonia and Motor Neuropathy." (PMID 35893067, 2022). "Lastly, mutations in SCP2 have been reported to cause leukoencephalopathy with dystonia and motor neuropathy [MIM: 613724] and azoospermia." (PMID 35996156, 2022). "Interestingly, the Scp2 locus has been linked to dystonia and motor neuropathy in human, pathology that can explain this reduced activity." (PMID 27097688, 2016). "Mutations in the sterol carrier protein-2 (SCP2) gene (OMIM #613724) cause a complex phenotype characterized by leukencephalopathy, dystonia, torticollis, azoospermia, cerebellar ataxia, and gait impairment." (PMID 30744104, 2019). "Motor neuropathy and dystonia was not shown at 39 months of age, but considering the size of the deletion and the deficits shown in the other patients with deletion of SCP2, future neurologic disorder are conceivable." (PMID 33157955, 2020).
Leukoencephalopathy (5 papers, 2020 to 2022). This term describes abnormality of the white matter of the cerebrum resulting from damage to the myelin sheaths of nerve cells. "Three genes in the region: ORC1, SCP2, DAB1, may be candidates for the main phenotypes observed in our patient such as short stature, microcephaly, growth retardation, leukoencephalopathy and DD/ID." (PMID 33157955, 2020).
glioma (4 papers, 2019 to 2025). A benign or malignant brain and spinal cord tumor that arises from glial cells (astrocytes, oligodendrocytes, ependymal cells). "It has been reported that SCP2 expression was upregulated in gliomas, with its expression levels found to correlate with the grades of gliomas." (PMID 40620061, 2025). "SCP2 was reported to be upregulated in gliomas, and the levels of its expression were found to be correlated with glioma grades." (PMID 37511575, 2023). "It has been reported that the expression of SCP2 is related to the progression of glioma, and the suppression of SCP2 protein expression can inhibit the proliferation of tumor cells by inducing autophagy." (PMID 34124063, 2021). "SCP2 has been reported to promote the proliferation of glioma cells by inhibiting apoptosis and inducing cell cycle progression through AKT-related signaling pathways." (PMID 31519191, 2019). "SCP2 expression has been reported to be related to the progression of gliomas, and downregulating SCP2 protein expression could suppress tumor cell proliferation by inducing autophagy." (PMID 31519191, 2019).
hepatoma (3 papers, 2018 to 2025). "Moreover, hepatocellular carcinoma cells overexpressing SCP2 are more susceptible to cholesterol hydroperoxides (7α‐OOH) damage." (PMID 40620061, 2025). "Overexpression of SCP-2 in McA-RH7777 rat hepatoma cells sharply increases the rate of the transfer of newly synthesized cholesterol from ER to PM and the amount of newly synthesized cholesterol in the secreted HDL." (PMID 30174957, 2018). "Because the SCP-2 overexpression stimulates cholesterol transport from ER to PM and stimulates secretion of cholesterol with HDL in hepatoma cells, the SCP-2 overexpression in L-cell fibroblasts inhibits cholesterol efflux to HDL at HDL concentration below 100 μg/ml." (PMID 30174957, 2018). "In addition, SCP2/SCPx enhanced cholesterol transport from the plasma membrane to ER for esterification by ACAT in L-cells and enhanced intracellular cholesterol cycling in hepatoma cells." (PMID 36292972, 2022).
pituitary adenomas (3 papers, 2019 to 2023). "In addition, SCP2-mediated cholesterol membrane transport promotes pituitary adenoma growth by activating hedgehog signaling." (PMID 34124063, 2021).
Zellweger syndrome (3 papers, 2016 to 2024). "SCP2 gene mutations are involved in the occurrence of Zellweger syndrome, which is characterized by cellular deficiency in peroxisomes with reduced synthesis of bile acids." (PMID 39456672, 2024). "Sterol carrier protein-2 (SCP2), also called nonspecific lipid-transfer protein, is thought to play a major role in intracellular lipid transport and metabolism, and it has been associated with diseases involving abnormalities in lipid trafficking, such as Zellweger syndrome." (PMID 26901662, 2016).
Obesity (2 papers, 2016 to 2021). Accumulation of substantial excess body fat. "Acat2 and Scp2 are involved in lipid metabolism while Acot11 is involved in obesity." (PMID 27699085, 2016).
pancreatic carcinoma (2 papers, 2021 to 2025). "SCP2 regulates angiogenesis and tumor migration, and the expression of SCP2 in pancreatic carcinoma cells effectively inhibits angiogenesis and cell cycle progression." (PMID 40620061, 2025).
atherosclerosis (1 paper, 2023). A disease characterized by the build-up of fatty material and calcium deposition in the arterial wall resulting in partial or complete occlusion of the arterial lumen. "In contrast to the protective effect of SCP2 on NAFLD, a previous study showed that SCP2 can promote the accumulation of low-density lipoprotein cholesterol (LDL-C), thereby promoting the development of atherosclerosis and hyperlipidemia." (PMID 38115130, 2023).
autism (1 paper, 2023). Persistent deficits in social interaction and communication and interaction as well as a markedly restricted repertoire of activity and interest as well as repetitive patterns of behavior. "Out of these 6 autism-related genes, only 3 (CPT2, SCP2 and SSBP3) have strong orthologs in flies (DIOPT Score >0.5), with the highest orthology for SSBP3 (DIOPT Score = 0.93)." (PMID 37486945, 2023).
breast adenocarcinoma (1 paper, 2024). "SCP2 was also involved in recurrent fusions with ECHDC2 and FAF1 in breast adenocarcinomas." (PMID 39038933, 2024).
cardiac arrest (1 paper, 2013). Cessation of breathing and/or cardiac function. "Possibly, atrioventricular changes induced by high phytanic acid levels led to cardiac arrest as reported for Scp2-knockout mice." (PMID 23459139, 2013).
delirium (1 paper, 2025). A disorder characterized by confusion; inattentiveness; disorientation; illusions; hallucinations; agitation; and in some instances autonomic nervous system overactivity. "Mediation analysis indicated that 3-hydroxyoctanoate partially mediated the causal association between sterol carrier protein 2 (SCP2) and delirium, accounting for approximately 19.23% of the total effect." (PMID 41330563, 2025). "The mediation analysis showed that 3-hydroxyoctanoate levels (GCST90026083) accounted for approximately 19.23% of the impact of SCP2 on delirium risk, with a 95% confidence interval (CI) of 0.49 to 37.97%, and Z = 2.011 (p = 0.044)." (PMID 41330563, 2025). "Additionally, the mediation analysis revealed that CSF 3-hydroxyoctanoate levels mediate the causal effect of SCP2 on delirium." (PMID 41330563, 2025). "The present work reveals that mitochondrial-related genes and CSF metabolites may play causal roles in delirium and highlights SCP2–3-hydroxyoctanoate as a novel molecular axis." (PMID 41330563, 2025). "There were eight protective genes (DHODH,DHRS7B,TOP1MT,CASP8,GFM1,CPT1B,TK2,GPD2), and four genes (SCP2,DMPK,GSTK1,SIRT3) that increased delirium risk, as shown inFigure 2, withp = 0.05 (dotted line); and false discovery rate (FDR) < 0.05 (red asterisks)." (PMID 41330563, 2025). "This study did not provide direct mechanistic experiments to confirm the biological interaction between SCP2 and 3-hydroxyoctanoate in delirium." (PMID 41330563, 2025). "Additionally, we calculated the proportion of indirect effects using mediation analyses, which suggested that only the level of 3-hydroxyoctanoate had a significant mediating effect of SCP2 on the development of delirium (19.2%,p < 0.05)." (PMID 41330563, 2025). "Our study revealed a novel SCP2–3-hydroxyoctanoate-delirium molecular axis." (PMID 41330563, 2025).
dysrhythmia (1 paper, 2025). "Likewise, a mutation in the SCP2 gene, encoding the SCPx enzyme, was present in a patient who exhibited progressive neurodegeneration, cardiac dysrhythmia, and metabolic abnormalities, including altered fatty acid levels and disrupted β-oxidation pathways." (PMID 39857412, 2025).
esophageal cancer (1 paper, 2021). A primary or metastatic malignant neoplasm involving the esophagus. "This study is the first to reveal the important role of SCP2 in esophageal cancer." (PMID 34124063, 2021).
gallstones (1 paper, 2011). Solid crystalline precipitates in the biliary tract, usually formed in the gallbladder, resulting in the condition of cholelithiasis. "SCP2 may be a genetic factor influencing the susceptibility to the formation of gallstones under the same life environment, and overexpression of SCP2 could be one of the important causes of cholesterol gallstones." (PMID 21310066, 2011). "The mRNA and protein expression of SCP2 was significantly increased in cholesterol gallstone patients compared to those of non-gallstone patients." (PMID 21310066, 2011). "Sterol Carrier Protein 2 (SCP2) participates in cholesterol trafficking and lipid metabolism in hepatocytes and may play a key role in cholesterol gallstone formation." (PMID 21310066, 2011). "Further studies on susceptible mice found that Lith 1 gene might result in overexpression of SCP2 mRNA during the formation of gallstones." (PMID 21310066, 2011). "The mRNA expression of liver SCP2 in 28 hereditary patients, 30 non-hereditary cholesterol gallstone patients and 32 non-gallstone patients was measured by Reverse Transcription Polymerase Chain Reaction (RT-PCR)." (PMID 21310066, 2011).
GM2 gangliosidosis (1 paper, 2015). A group of recessively inherited diseases characterized by the intralysosomal accumulation of G(M2) GANGLIOSIDE in the neuronal cells. "Notably, mice that are deficient in enzymes that we found to be downregulated in the Mwk cerebellum also display cerebellar dysfunction including Scp2 knockout mice, Smpd1-deficient mice, a model of Niemann-Pick disease, and Gm2a knockout mice, a model of GM2-gangliosidosis." (PMID 25908616, 2015).
liver cancer (1 paper, 2021). An epithelial or non-epithelial malignant neoplasm that arises from the liver. "We found that three genes ACOX2, ALDH8A1, and SCP2 were not reported in-depth in liver cancer." (PMID 33414412, 2021).
Menière's disease (1 paper, 2021). "From our identified miRNAs, miRNA-1299 was identified as the most promising biomarker for Menière's disease since it is differentially regulated in both perilymph and serum of Menière's patients, and is predicted to target R3HDM2, SCP2, and ATP5PO mRNA." (PMID 34220670, 2021).
osteoarthritis (1 paper, 2023). A noninflammatory degenerative joint disease occurring chiefly in older persons, characterized by degeneration of the articular cartilage, hypertrophy of bone at the margins and changes in the synovial membrane. "Sterol carrier protein 2 (SCP2) is highly expressed in human osteoarthritis (OA) cartilage, accompanied by ferroptosis hallmarks, especially the accumulation of lipid hydroperoxides (LPO)." (PMID 37422468, 2023).
schizophrenia (1 paper, 2021). A major psychotic disorder characterized by abnormalities in the perception or expression of reality. "In addition, Ndufs2 was associated with schizophrenia terms and Scp2 was associated with alcohol-related terms." (PMID 34367237, 2021).
Stroke (1 paper, 2016). Sudden impairment of blood flow to a part of the brain due to occlusion or rupture of an artery to the brain. "Grb2, Acot11, Acat2, Scp2, Anp32b and Ppp2r5d were down-regulated after stroke." (PMID 27699085, 2016).
triple-negative breast carcinoma (1 paper, 2017). An invasive breast carcinoma which is negative for expression of estrogen receptor (ER), progesterone receptor (PR), and human epidermal growth factor receptor 2 (HER2). "When investigating the effects of everolimus on the osteoclastogenesis of peripheral blood monocytes in a coculture model with the triple-negative breast cancer cell line SCP2, everolimus was effective at inhibiting osteoclastogenesis induced by SCP2-derived factors." (PMID 28793923, 2017).
type 2 diabetes (1 paper, 2022). "In agreement with our study, hepatic SCP2 expression was reduced in diabetic rat, WIPI1 expression were decreased in skeletal muscle from type 2 diabetes, decreased PRKAA1/AMPK phosphorylation was observed in high glucose-induced HK-2 cells." (PMID 35992146, 2022).